ZNF44 (zinc finger protein 44)
Description:
May be involved in transcriptional regulation.
Synonyms: GIOT-2; KOX7; ZNF55; ZNF58; ZNF504; ZNF
Tractability: PROTAC: ubiquitination databases record sites on it.
Gene: Protein-coding gene on chromosome 19 (12,224,686 to 12,294,883, reverse strand). Ensembl gene ENSG00000197857.
Subcellular location: Nucleus
Subcellular location (Human Protein Atlas): Nucleoplasm; Cytosol; Microtubules
Gene Ontology:
Molecular function: DNA-binding transcription factor activity, RNA polymerase II-specific; RNA polymerase II transcription regulatory region sequence-specific DNA binding
Biological process: regulation of transcription by RNA polymerase II; regulation of DNA-templated transcription
Cellular component: nucleus
Genetic constraint (gnomAD): Loss-of-function variants: 6 observed, 8.17 expected, observed/expected ratio (o/e) 0.73, 90% interval 0.4 to 1.44. That is too few expected variants to judge how well the gene tolerates losing a copy. Missense variants: 676 observed, 753.02 expected, observed/expected ratio (o/e) 0.9, 90% interval 0.84 to 0.96. Synonymous variants: 219 observed, 246.55 expected, observed/expected ratio (o/e) 0.89, 90% interval 0.8 to 0.99.
Homologues: Orthologues: chimpanzee ZNF44 (99% identical), macaque ZNF44 (97% identical), rat Zfp617 (33% identical), mouse Zfp961 (32% identical). Paralogues in human: ZNF823 (75% identical), ZNF443 (74% identical), ZNF799 (74% identical), ZNF442 (71% identical), ZNF441 (62% identical), ZNF700 (57% identical), ZNF709 (57% identical), ZNF563 (56% identical), ZNF433 (56% identical), ZNF14 (52% identical), ZNF791 (52% identical), ZNF878 (47% identical), and 3 more.
Diseases named in the same sentence as ZNF44 in open-access papers:
ZNF44 is named in the same sentence as 1 disease in open-access papers, as found by Europe PMC text mining. Sharing a sentence is not in itself a finding about the gene and the disease.
ZNF44 shares sentences with these, for which no sentence is quoted: Hypertension (1 paper).